ADAMTS9-AS2 (ADAMTS9 antisense RNA 2)
Gene: Long non-coding RNA gene on chromosome 3 (64,684,879 to 65,061,892, forward strand). Ensembl gene ENSG00000241684.
Diseases named in the same sentence as ADAMTS9-AS2 in open-access papers:
ADAMTS9-AS2 is named in the same sentence as 15 diseases in open-access papers, as found by Europe PMC text mining. Sharing a sentence is not in itself a finding about the gene and the disease. The quoted sentences say what the papers report.
glioma (5 papers, 2018 to 2024). A benign or malignant brain and spinal cord tumor that arises from glial cells (astrocytes, oligodendrocytes, ependymal cells). "In a glioma study, ADAMTS9-AS2 was found to be significantly downregulated in tumor tissues compared with normal ones and reversely associated with tumor grade and prognosis." (PMID 32675385, 2020). "Moreover, limited information is available regarding ADAMTS9-AS2, a gene whose expression is observed to be downregulated in glioma, correlating with the grade of the glioma." (PMID 38534769, 2024). "ADAMTS9-AS2 (ADAMTS9 antisense RNA 2) is an antisense lncRNA with unknown function, recently reported as a tumor suppressor gene in glioma and associated with senile neurodegeneration and AD." (PMID 33076555, 2020).
breast carcinoma (3 papers, 2020 to 2025). "ADAMTS9-AS2 (ADAMTS9 antisense RNA 2) was described in chemoresistance in some types of cancer, including renal and glioblastoma, besides breast cancer." (PMID 34359587, 2021). "ADAMTS9-AS2 is downregulated in tamoxifen-resistant cells derived from MCF7, and downregulation of ADAMTS9-AS2 is also observed in breast cancer tissues, especially in breast tumors with grade III–IV or a tumor size larger than 2 cm." (PMID 32486413, 2020). "In Tam-resistant breast cancer tissues and cell lines, ADAMTS9-AS2 is downregulated." (PMID 34359587, 2021).
neuroblastoma (1 paper, 2023). Neuroblastoma (NB) is the most common solid, extracranial childhood tumor. "The observed differential expression of ADAMTS9-AS2 in neuroblastoma cells was caused by m6A methylation." (PMID 37991019, 2023). "We analyzed whether m6A modification is associated with the diverse expression of ADAMTS9-AS2 in neuroblastoma." (PMID 37991019, 2023).
ovarian carcinoma (1 paper, 2021). A malignant neoplasm originating from the surface ovarian epithelium. "Studies have demonstrated that ADAMTS9‐AS2 inhibits proliferation, cell migration and invasion, and induces apoptosis in the lung, gastric and ovarian cancer cells." (PMID 33345447, 2021).
tumor (7 papers, 2020 to 2025). "ADAMTS9-AS2 (Ensembl, ENSG00000241684) has been linked to several tumor-associated genes in multiple cancers." (PMID 36816363, 2023). "Exosomal ADAMTS9‐AS2 could transport to the cell microenvironment and exerts tumour‐suppressive roles like exogenous ADAMTS9‐AS2." (PMID 33345447, 2021). "Some studies reported that the ADAMTS9-AS2 is known as a tumor suppressor, so it inhibits the remodeling of extracellular matrix (ECM), which is a critical process for tumor invasive development." (PMID 41436994, 2025).
cancer (3 papers, 2019 to 2021). A tumor composed of atypical neoplastic, often pleomorphic cells that invade other tissues. "However, relevant research on ADAMTS9‐AS2 in cancer is still limited." (PMID 31144439, 2019).
ADAMTS9-AS2 also shares sentences with these, for which no sentence is quoted: clear cell renal cell carcinoma (2 papers); glioblastoma (2); lung carcinoma (2); bladder cancer (1); breast tumors (1); colorectal cancer (1); esophageal cancer (1); gastric cancer (1); hepatocellular carcinoma (1).